Y_RNA (Y RNA )
Gene: Miscellaneous RNA gene on chromosome 5 (72,768,702 to 72,768,811, forward strand). Ensembl gene ENSG00000206770.
Homologues: Orthologues: chimpanzee Y_RNA (100% identical), macaque Y_RNA (95% identical). Paralogues in human: RNY1P5 (87% identical), Y_RNA (87% identical), Y_RNA (86% identical), Y_RNA (85% identical), Y_RNA (84% identical), Y_RNA (83% identical), Y_RNA (82% identical), RNY1P1 (81% identical), RNY1P6 (81% identical), Y_RNA (81% identical), Y_RNA (80% identical), RNY1 (79% identical), and 95 more.